PCDHGA5 (protocadherin gamma subfamily A, 5)
Description:
Potential calcium-dependent cell-adhesion protein. May be involved in the establishment and maintenance of specific neuronal connections in the brain.
Synonyms: PCDH-gamma-A5; CDH-GAMMA-A5; ME3
Tractability: Antibody: UniProt places it where antibodies can reach, with medium confidence; UniProt predicts a signal peptide or a membrane-spanning region; its Gene Ontology location is reachable by antibodies, with medium confidence.
Gene: Protein-coding gene on chromosome 5 (141,364,162 to 141,512,975, forward strand). Ensembl gene ENSG00000253485.
Subcellular location: Cell membrane
Subcellular location (Human Protein Atlas): Plasma membrane; Vesicles; Cytosol; Nucleoplasm
Gene Ontology:
Molecular function: cell adhesion molecule binding; calcium ion binding
Biological process: cell adhesion; homophilic cell-cell adhesion
Cellular component: plasma membrane; membrane
Genetic constraint (gnomAD): Loss-of-function variants: 36 observed, 59.88 expected, observed/expected ratio (o/e) 0.6, 90% interval 0.46 to 0.79. The upper end of that interval is the gene's LOEUF score, 0.79, which puts it in group 3 of 6, group 1 being the genes least tolerant of losing a copy. Missense variants: 1,305 observed, 1,277.5 expected, observed/expected ratio (o/e) 1.02, 90% interval 0.98 to 1.07. Synonymous variants: 563 observed, 558.94 expected, observed/expected ratio (o/e) 1.01, 90% interval 0.94 to 1.08.
Homologues: Orthologues: mouse Pcdhga5 (85% identical). Paralogues in human: PCDHGA4 (76% identical), PCDHGA6 (76% identical), PCDHGA7 (75% identical), PCDHGA2 (75% identical), PCDHGA3 (75% identical), PCDHGA8 (75% identical), PCDHGA10 (75% identical), PCDHGA1 (75% identical), PCDHGA12 (74% identical), PCDHGA11 (74% identical), PCDHGA9 (73% identical), PCDHGB5 (53% identical), and 49 more.
Diseases named in the same sentence as PCDHGA5 in open-access papers:
PCDHGA5 is named in the same sentence as 5 diseases in open-access papers, as found by Europe PMC text mining. Sharing a sentence is not in itself a finding about the gene and the disease. The quoted sentences say what the papers report.
chronic bronchitis (1 paper, 2024). A type of chronic obstructive pulmonary disease characterized by chronic inflammation in the bronchial tree that results in edema, mucus production, obstruction, and reduced airflow to and from the lung alveoli. "Expression of only PCDHGA5 as a tight junction gene increased in the wood smoke exposed chronic bronchitis-like bronchial model." (PMID 38245732, 2024).
Wolf-Hirschhorn syndrome (1 paper, 2022). Wolf-Hirschhorn syndrome (WHS) is a developmental disorder characterized by typical craniofacial features, prenatal and postnatal growth impairment, intellectual disability, severe delayed psychomotor development, seizures, and hypotonia. "PCDHGA5 is a protein coding gene associated with Wolf-Hirschhorn Syndrome, which is caused by the deletion of a region of chromosome 4." (PMID 35428183, 2022).
PCDHGA5 also shares sentences with these, for which no sentence is quoted: bipolar affective disorder (1 paper); neurodevelopmental disorder (1); Usher syndrome type 1 (1).